PNMA6A (PNMA family member 6A)
Synonyms: PNMA6C; MGC15827; MA6; PNMA6
Tractability: PROTAC: ubiquitination databases record sites on it.
Gene: Protein-coding gene on chromosome X (153,072,454 to 153,075,019, forward strand). Ensembl gene ENSG00000235961.
Subcellular location (Human Protein Atlas): Mitochondria
Gene Ontology:
Molecular function: protein binding
Homologues: Orthologues: dog PNMA6A (75% identical). Paralogues in human: PNMA6F (48% identical), PNMA6E (45% identical), PNMA3 (41% identical), PNMA5 (39% identical), PNMA1 (38% identical), PNMA2 (37% identical), MOAP1 (35% identical), PNMA8A (24% identical), ZCCHC12 (23% identical), ZCCHC18 (23% identical), PNMA8B (18% identical), CCDC8 (17% identical), and 1 more.
Diseases named in the same sentence as PNMA6A in open-access papers:
PNMA6A is named in the same sentence as 9 diseases in open-access papers, as found by Europe PMC text mining. Sharing a sentence is not in itself a finding about the gene and the disease. The quoted sentences say what the papers report.
meningioma (1 paper, 2021). A generally slow growing tumor attached to the dura mater. "One genetic variant involving the PNMA6A gene was present in 1/3 meningiomas investigated." (PMID 34868937, 2021). "Overall, WHO grade 1 meningiomas harbored numerous and heterogeneous genetic variants, which most frequently affected the NF2 (47%) gene and to a less extent the PNMA6A (22%), TIGD1 (16%), SMO (13%), PTEN (13%), CREG2 (9%), EEF1A1 (6%), POLR2A (6%), ARID1B (3%), and FAIM3 (3%) genes." (PMID 34868937, 2021). "Another four genes (PNMA6A, TIGD1, PTEN, and SMO) were found to be altered in >10% of all WHO grade 1 meningiomas investigated, while the remaining CREG2, EEF1A1, and POLR2A genes were recurrently altered in a minority (<10%) of cases." (PMID 34868937, 2021).
PNMA6A also shares sentences with these, for which no sentence is quoted: breast carcinoma (1 paper); cancer (1); colorectal cancer (1); infection (1); lung carcinoma (1); parasitemia (1); prostate carcinoma (1); tumor (1).